DLL1 (delta like canonical Notch ligand 1)
Diseases named in the same sentence as DLL1 in open-access papers (continued):
Sharing a sentence is not in itself a finding about the gene and the disease.
renal carcinoma (2 papers, 2015 to 2020). A carcinoma arising from the epithelium of the renal parenchyma or the renal pelvis. "Knockdown of UCA1 increased DLL1, Jag1, Jag2 and Notch1expression and decreased DLL4, NICD and Hes1 expression in renal cancer cells." (PMID 31996265, 2020). "We found knockdown of UCA1 increased DLL1, Jag1, Jag2 and Notch1expression and decreased DLL4, NICD and Hes1 expression of renal cancer cells in vivo." (PMID 31996265, 2020).
spondylocostal dysostosis (2 papers, 2022 to 2024). Spondylocostal dysplasia is a rare genetic disorder characterized by defects of the bones of the spine (vertebrae) and abnormalities of the ribs. "Mutations in human DLL1 induce neurodevelopmental disorders with non-specific brain abnormalities, whereas mutations in DLL3 cause spondylocostal dysostosis with axial skeletal defects." (PMID 35422684, 2022).
type 1 diabetes (2 papers, 2015 to 2018). "An interesting gene located in this part of the pig genome, delta-like 1 (Drosophila) (DLL1), seems associated to type 1 diabetes in humans." (PMID 25821781, 2015). "Additionally, a SNP in an intra-genic region spanning several genes including DLL1 has been associated with type 1 diabetes (T1D)." (PMID 30212457, 2018).
acute promyelocytic leukemia (1 paper, 2013). An aggressive form of acute myeloid leukemia (AML), characterized by arrest of leukocyte differentiation at the promyelocyte stage, due to a specific chromosomal translocation t(15;17) in myeloid cells. "Very recently, Jagged1 and Dll1 were shown to be expressed at significantly higher levels in acute promyelocytic leukemia (APL) samples compared with all other subtypes, as well as normal myeloid populations." (PMID 24252593, 2013).
age-related macular degeneration (1 paper, 2021). Age-related loss of vision in the central portion of the retina (macula), secondary to retinal degeneration. "DLL1 is required for normal eye development while EFEMP1 has been implicated in age-related macular degeneration and is also associated with Malattia Leventinese and Doyne honeycomb retinal dystrophy." (PMID 34638643, 2021).
Alagille syndrome (1 paper, 2014). "For example, except for the common disease gene JAG1 between Tetralogy of Fallot and Alagille syndrome, the two diseases interact through 5 PPIs with a p value < < 0.01 in the network, including JAG1 – NOTCH1, JAG1 – NOTCH2, JAG1 – NOTCH3, DLL1 - NOTCH2 and DLL1 – NOTCH3." (PMID 25539592, 2014).
Alzheimer disease (1 paper, 2015). A progressive, neurodegenerative disease characterized by loss of function and death of nerve cells in several areas of the brain leading to loss of cognitive function such as memory and language. "The findings that Notch and Dll1 are substrates of the γ-secretase complex and that Notch signaling participates in learning and memory and microtubule dynamics imply a potential link between Notch signaling and Alzheimer’s disease (AD) pathogenesis." (PMID 26355680, 2015).
ameloblastoma (1 paper, 2020). The most common odontogenic tumor, arising from the epithelial component of the embryonic tooth and usually affecting the molar-ramus region of the mandible or maxilla. "Expression of NOTCH2 and NOTCH3 was associated with expression of the ligands JAG1, DLL1, and DLL4 in the ameloblastoma epithelium." (PMID 32155948, 2020). "We observed that NOTCH3, JAG1, DLL1, and DLL4 are also expressed within the ameloblastoma tumor mass." (PMID 32155948, 2020). "Some studies have reported the expression of NOTCH1, 2, and 3, as well as their ligands DLL1, DLL4, and JAG1, in all ameloblastomas analyzed." (PMID 32155948, 2020).
asthma (1 paper, 2024). "Research findings using rat models of asthma demonstrated that the presence of Notch1 and Notch2 on CD4+ T cells, along with Jagged1 on dendritic cells and/or Dll1 on smooth muscle cells, facilitated asthma development." (PMID 39450276, 2024).
astrocytomas (1 paper, 2020). "In a specific subset of astrocytomas, upregulation of Dll1 leads to an increased expression of HES6." (PMID 32796631, 2020).
Ataxia (1 paper, 2023). Ataxia refers to impaired coordination of voluntary muscle movement. "Additionally, the following clinical characteristics were reported in at least one patient with a heterozygous DLL1 variant: PNH, large cisterna magna, strabismus, feeding problems, sleep apnoea, recurrent infections, hemivertebrae, sacral dimple, joint hypermobility, ataxia and hyperactivity." (PMID 36935482, 2023).
autism spectrum disorder (1 paper, 2023). A spectrum of developmental disorders that includes autism, and Asperger syndrome. "In their cohort, 5 out of their 13 DLL1 variant patients and their one DLL1 deletion patient had autism spectrum disorder." (PMID 36935482, 2023).
autoimmune encephalitis (1 paper, 2016). Inflammation of the brain secondary to an immune response triggered by the body itself. "Dll1−/− mice exhibited lower clinical scores of experimental autoimmune encephalitis than control mice." (PMID 27659682, 2016).
Autoimmunity (1 paper, 2017). The occurrence of an immune reaction against the organism's own cells or tissues. "Jag1 and Dll4 have opposite effects on sprouting angiogenesis and differential effects of Jag1 and Dll1,4 have been described on T cells proliferation and the regulation of T cell effector functions in autoimmunity." (PMID 28472949, 2017).
Bradycardia (1 paper, 2009). A slower than normal heart rate (in adults, slower than 60 beats per minute). "The Dll1 haploinsufficient animals are smaller, lighter, with altered fat to lean ratio and have an increased blood pressure and a slight bradycardia." (PMID 19562077, 2009).
brain tumor (1 paper, 2020). "This is true for Notch receptors and canonical Notch ligands such as Dll1 and Jag1 —some of the closest relatives to DLK1—and for proteins involved in brain tumor and neural stem cell maintenance like CD44 and p75NTR." (PMID 32205867, 2020).
CADASIL (1 paper, 2023). "Previous research has identified Notch3 as a diagnostic marker for cerebral autosomal dominant arteriopathy with subcortical infarcts and leukoencephalopathy (CADASIL), while DLL1 has shown utility in diagnosing tuberculous meningitis." (PMID 37063841, 2023).
Cerebellar dysplasia (1 paper, 2025). Cerebellar dysplasia (abnormal growth or development) is defined by abnormal cerebellar foliation, white matter arborization, and gray-white matter junction. "DLL1 deletion exhibited altered brain structures, the most prevalent abnormalities were cerebellar dysplasia, increased ventricle width, and corpus callosum anomalies (observed in over 70% of cases)." (PMID 41190327, 2025).
chondrosarcoma (1 paper, 2020). A malignant cartilaginous matrix-producing mesenchymal neoplasm arising from the bone and soft tissue. "Another miRNA, miR-34a, has been reported to noticeably inhibit the expression of DLL1, trigger cell death and senescence, suppress proliferation, and prevent scratch assay wound closure in rat chondrocytes and chondrosarcoma cells, therefore facilitating the development of OA." (PMID 32062610, 2020).
cleft palate (1 paper, 2023). Cleft palate is a fissure type embryopathy that affects the soft and hard palate to varying degrees. "This DLL1 variant patient also had a cleft palate, but no further phenotype information was given." (PMID 36935482, 2023).
cognitive deficits (1 paper, 2022). "In the context of cognitive deficits after TBI, we found that several inflammations and immune-related genes (Mterf1a, Trp73, Cd3d, Dll1, and Il5) had abnormal expression levels lncRNAs may potentially target." (PMID 35311004, 2022).
colitis (1 paper, 2014). Inflammation of the colon. "Analysis showed a surprising loss of Dll1 expression in the crypts of DSS-colitis mice." (PMID 24860699, 2014). "Conversely, a striking increase in the number of Dll4+ve IECs was observed in the crypts of those DSS-colitis mice, suggesting that a distinct regulation of Dll1 and Dll4 expression exists under the inflammatory environment." (PMID 24860699, 2014). "We also found that the dominance of Dll1+ve or Dll4+ve IECs within the colonic crypt significantly shifts to Dll4+ve IECs in DSS-colitis mice." (PMID 24860699, 2014). "Compared to the normal colon, analysis of DSS-colitis showed that number of Dll1+ve IECs significantly decrease in the elongated crypts of the inflamed colonic mucosa." (PMID 24860699, 2014). "Double staining with Hes1 confirmed that a rare population of Dll1+ve IECs, as well as the dominant Dll4+ve IECs clearly located adjacent to Hes1+ve IECs within the elongated crypts of the DSS-colitis mice." (PMID 24860699, 2014). "Quantitative analysis confirmed that number of Dll1+ve IECs significantly decrease, whereas that of Dll4+ve IECs significantly increase in DSS-colitis mice, compared to control mice." (PMID 24860699, 2014). "Also, the analysis showed that both Dll1+ve and Dll4+ve IECs that were found in the DSS-colitis mice maintain their expression of ATOH1." (PMID 24860699, 2014). "Therefore, we examined the expression of Dll1 and Dll4 in tissues of DSS-colitis mice." (PMID 24860699, 2014).
colorectal adenoma (1 paper, 2020). An adenoma that arises from the colon or rectum. "We investigated mRNA expression of four Notch receptors (Notch1–4), five ligands (Jag1, Jag2, Dll1, Dll3, and Dll4), and four target genes (Hes1, Hes5, Hey1, and Hey2) using highly specific TaqMan gene expression assays in colorectal adenomas and cancers." (PMID 32211044, 2020).
delirium (1 paper, 2025). A disorder characterized by confusion; inattentiveness; disorientation; illusions; hallucinations; agitation; and in some instances autonomic nervous system overactivity. "Additionally, the study will examine its association with postoperative delirium (POD), since notch signaling, which is regulated by DLL1, plays a key role in neuronal development and the regulation of neuronal apoptosis induced by neuro-inflammation." (PMID 40775336, 2025).
Depression (1 paper, 2025). "Depression-associated pairs spanned Notch (JAG1-NOTCH2, DLL1-NOTCH3, DLL4-NOTCH3), ephrin (EFNA5-EPHA5, EFNA5-EPHA7, EFNA5-EPHA4), and extracellular matrix pathways (SLIT1-ROBO1, NTN1-DCC)." (PMID 40964296, 2025).
Down syndrome (1 paper, 2022). "Moreover, the Notch signalling pathway and its associated components such as Delta-like 1 (Dll1) and Hes-1 have been reported to be hyperactivated in the cortex of patients with Down syndrome, as observed in AD." (PMID 35291879, 2022). "However, Down syndrome fibroblasts and AD cortex show similar overexpression patterns with respect to Notch-1 and Dll1, thereby suggesting that augmented Aβ production and neurodegeneration." (PMID 35291879, 2022).
dry eye (1 paper, 2015). "A recent report showed that members of the canonical Notch signaling pathway i.e., Notch1, Notch2, Notch3, Jagged1, Dll1, were significantly down-regulated in dry eye as compared to the non-dry eye conjunctival epithelia." (PMID 26818247, 2015).
embryonic carcinoma (1 paper, 2012). "The overexpression of DLL1-ICD induces neuron formation in P19 embryonic carcinoma cells, but it was also reported that DLL1-ICD induces growth arrest by inducing expression of the cell cycle inhibitor p21 in several cell types." (PMID 23300864, 2012).
endometrial adenocarcinoma (1 paper, 2016). "The consistent increase in mir-34a level in EAC, accompanied by a decrease in NOTCH1 and DLL1 levels, suggests that mir-34a may serve as a molecular marker of neoplastic transformation in endometrial adenocarcinoma." (PMID 27039384, 2016). "Furthermore, our study is the first to identify a correlation between mir-34a and its target genes NOTCH1 and DLL1 in endometrial adenocarcinoma." (PMID 27039384, 2016).
endometrial cancer (1 paper, 2016). Primary or metastatic malignant neoplasm involving the endometrium (mucous membrane that lines the endometrial cavity). "To verify whether mir-34a is a regulator of NOTCH1 and DLL1 in human endometrial cancer cells, we designed experiments of gain- and loss-of-function of mir-34a in the Ishikawa cell line." (PMID 27039384, 2016).
experimental autoimmune encephalomyelitis (1 paper, 2012). An autoimmune demyelinating disease of the central nervous system that is produced experimentally in animals by the injection of homogenized brain or spinal cord in Freund's adjuvant. "Accordingly, we previously demonstrated that Dll1 blockade ameliorated experimental autoimmune encephalomyelitis while Jagged1 blockade exacerbated it." (PMID 22390640, 2012).
gram-negative bacterial infections (1 paper, 2020). Infections caused by bacteria that show up as pink (negative) when treated by the gram-staining method. "For instance, the upregulation of DLL-1 and Notch target genes in primary human monocytes was reported following in vitro gram-positive and gram-negative bacterial infection." (PMID 31906482, 2020). "Consistently, in gram-positive and gram-negative bacterial infection models, IL-6 was noted to induce the expression of DLL-1 in primary human monocytes through activation of transcription factor STAT-3." (PMID 31906482, 2020).
hepatocellular carcinoma (1 paper, 2022). A malignant tumor that arises from hepatocytes. "In hepatocellular carcinoma cells, POFUT1 overexpression promoted the binding of the Notch ligand DLL1 to the Notch receptor, and then activated the Notch signaling pathway, indicating that an aberrantly activated POFUT1-Notch pathway is involved in HCC progression." (PMID 35335147, 2022).
limb ischemia (1 paper, 2020). A ischemia that involves the limb. "Next, we assessed the regulation of miR-24-3p, Notch-1, and Dll-1 in muscle-resident microvascular cells exposed to hypoxia in the setting of mouse limb ischemia." (PMID 32138369, 2020).
lymphoma (1 paper, 2012). A malignant (clonal) proliferation of B- lymphocytes or T- lymphocytes which involves the lymph nodes, bone marrow and/or extranodal sites. "Therefore we examined the mRNA levels of the lymphoma-related proto-oncogenes involved in the Notch-1 signal pathway, including Notch-1, DLL1/4, Hes-1, PTEN and c-Myc in the liver tissues of individual animals." (PMID 23145171, 2012).
lymphopenia (1 paper, 2022). Reduction in the number of lymphocytes. "Anti-Dll1 antibodies profoundly inhibited all phenotypic changes and subsequent proliferation induced by lymphopenia in FoB cells." (PMID 35579963, 2022). "Mechanistically, Dll1/Notch2-mediated signals were essential for lymphopenia-induced B cell transdifferentiation, for their proliferation, and for their subsequent differentiation into antibody-producing plasma cells." (PMID 35579963, 2022). "Thus, Dll1-Notch2 interactions were the major drivers of the Notch-mediated B cell response to lymphopenia." (PMID 35579963, 2022). "Normal MZB cells rely on the interaction of Notch2 receptors with Dll1 Notch ligands, although Dll4 Notch ligands are also expressed in the spleen and could become engaged in the setting of lymphopenia." (PMID 35579963, 2022). "Dll1-expressing Ccl19-Cre+ stromal cells drive the B cell response to lymphopenia." (PMID 35579963, 2022).
MELAS (1 paper, 2020). "However, by day 35, mRNA expressions of Notch receptor NOTCH1, NOTCH receptor ligands DLL1 and JAG1 as well as the downstream targets HEY1 and HES5 were significantly higher in day 35 MELAS compared to controls." (PMID 32170107, 2020).
MRKH syndrome (1 paper, 2015). "Recently, a valuable gene expression profile of in vitro cultured vaginal tissue from MRKH syndrome patients has identified dysregulation of MUC1, WNT7A, JAG1 and DLL1, emphasizing the critical role of canonical Wnt signaling and the NOTCH pathway." (PMID 26075712, 2015).
pancreatic cancer (1 paper, 2016). "In vitro studies, applying a COX-2-selective inhibitor to COX-2-positive pancreatic cancer cells, revealed that expression of Notch1, Hes1 and DLL1 depended on COX-2-mediated prostaglandin synthesis." (PMID 27381829, 2016).
psoriasis (1 paper, 2025). An autoimmune condition characterized by red, well-delineated plaques with silvery scales that are usually on the extensor surfaces and scalp. "DLL1 is the Notch ligand detected in the epidermis, and a previous study demonstrated increased expression of DLL4 in psoriasis lesional skin compared to unaffected skin." (PMID 40018044, 2025). "Thus, both DLL1 and DLL4 are likely to be detected in psoriasis lesional skin." (PMID 40018044, 2025). "However, DLL1 may be the first Notch ligand to induce Mo-LCs or DLL4 expression given that DLL1 is detected in unaffected skin and DLL4 expression increases in psoriasis lesional skin." (PMID 40018044, 2025).
renal fibrosis (1 paper, 2024). A final common manifestation of a wide variety of chronic kidney diseases characterized by glomerulosclerosis and tubulointerstitial fibrosis. "The expression of genes that promote renal fibrosis (Smad2, Smad3, Smad4, Shh, Dll1) was downregulated, while the expression of genes that inhibit renal damage (Smurf1, Smurf2, Smad1, Smad5, Smad6, Smad7) was increased in the WT+miPEP31 group (PEP1/2) compared with the WT+ cPEP (SCR1/2) group." (PMID 38992718, 2024).
schizophrenia (1 paper, 2022). A major psychotic disorder characterized by abnormalities in the perception or expression of reality. "Similarly, in the murine schizophrenia model treated with mesenchymal stem cells, long term improvement in social behavior was also positively correlated with the NOTCH ligand Dll1 gene expression in the hippocampus." (PMID 35159158, 2022).